IL6 (interleukin 6)
Diseases named in the same sentence as IL6 in open-access papers (continued):
Sharing a sentence is not in itself a finding about the gene and the disease.
COVID-19 (continued). "Obese patients develop severe COVID-19 sequelae, due to the high concentrations of TNF-α, MCP-1 and IL-6 produced in the meantime by visceral and subcutaneous adipose tissue and by innate immunity." (PMID 33160363, 2020). "Visceral adipose tissue-resident Tregs of lean individuals produce high levels of anti-inflammatory IL-10, which upregulates Th2 pathways, antagonizing effects of IL-6 and TNF, a mechanism also supposed to occur in COVID-19 patients." (PMID 33510644, 2020). "It was identified that serum IL-6, CRP, procalcitonin, and lactate at the time of being admitted to hospital predicted poor outcomes of COVID-19." (PMID 33239109, 2020). "Increased pro-inflammatory cytokines and neutrophils infiltration were present in severe COVID-19 patients, in our murine ARDS model, we noticed the increased pro-inflammatory cytokines IL-6, TNF-α, and IL-1α in BALF." (PMID 33584719, 2020). "Patients with COVID-19 show activation of both Th1 and Th2 pathways over the course of infection with significant levels of IFN-γ, IL-1β, and IL-6 as well as IL-4 and IL-10, respectively." (PMID 32983176, 2020). "The three families of monoclonal antibodies approved to treat rheumatoid arthritis are directed against IL-6, B lymphocyte surface protein CD20 and TNFα, three targets of potential interest for further investigation in COVID-19 treatment." (PMID 33519443, 2020). "A literature search was performed using the databases PubMed, EMBASE, and Web of Science to collect the levels of cytokine including IL-1β, IL-6, IL-18, TNF-α, IL-10, and ferritin in severe COVID-19 patients." (PMID 33552062, 2020). "High levels of IL-6, known as the critical point in the pathogenesis of COVID-19, imply that blocking it using monoclonal antibodies such as tocilizumab (RoActemra, Roche) and sarilumab (Kevzara, Sanofi), may constitute a therapeutic strategy in management of COVID-19 patients." (PMID 33244382, 2020). "The early study suggested that, with ensuing local inflammation of lung affected areas, secretion of the pro-inflammatory cytokines and chemokines was increasing, such as IL-6, IFNγ, M-CSF, and MCP1, and these would release into the blood of COVID-19 patients." (PMID 32903864, 2020). "Previously, small-scale studies have evaluated changes in IL-6 and CRP concentrations for COVID-19 patients, the correlation between IL-10 and CRP is still unclear." (PMID 32475230, 2020). "Tocilizumab is a monoclonal antibody targeting the receptor of IL-6; a pro-inflammatory cytokine involved in the pathogenesis of ARDS seen with COVID-19." (PMID 33510989, 2020). "Therefore, blocking the IL-6 pathway might reduce the vigorous inflammatory response in COVID-19." (PMID 32397399, 2020). "A detailed analysis of 1,484 patients with COVID-19 showed that TNF and IL-6 levels, independently correlated with disease outcome." (PMID 33574819, 2020). "Here, increases in CRP, IL-6, and TNF-α levels in severe cases compared to mild cases of COVID-19 were revealed." (PMID 33244370, 2020). "Among others, hydroxychloroquine (HCQ) and the interleukin-6 (IL-6) inhibitor, tocilizumab (TCZ), became popular options to treat COVID-19." (PMID 32784192, 2020). "In COVID-19 patients, the numbers of CD4+ and CD8+ T cells decreased, while the levels of IL-6 and IL-10 increased in severe cases." (PMID 33028689, 2020). "Similar to LHQW, these chemical compounds involved a variety of biological processes and pathways to treat COVID-19 by combining with key target proteins IL-6, ALB, and MAPK3, which supported the clinical application with COVID-19." (PMID 32483409, 2020). "Even the higher COVID-19 mortality rate observed in male compared to female patients may correlate with sex differences in the immune responses between male and female, with higher plasma levels cytokines and chemokines including IL-6, IL-8, IL-18, CCL5 found in male patients." (PMID 33362782, 2020).
COVID-19 (continued). "This is supported by cohort data from China, which report increased ferritin, and elevated TNF-α, IL-6 and IFN-γ levels in severe versus mild COVID-19-cases." (PMID 33106497, 2020). "We measured plasma concentrations of TNF, IL-1β, IL-6, IFN-β, IFN-γ, and IL-18 in a larger cohort of COVID-19 patients." (PMID 32651212, 2020). "Severe coronavirus disease 2019 (COVID-19) infection, particularly in those with acute respiratory distress syndrome (ARDS), is characterized by marked inflammation and immune activation with elevated levels of inflammatory cytokines, such as interleukin (IL)-6 and tumor necrosis factor." (PMID 33054818, 2020). "Although IL-10 levels were significantly higher in COVID-19 patients with SP, patients with DHF had 25-fold higher levels, whereas IL-6 levels were 11-fold higher in those with COVID-19 SP." (PMID 33199778, 2020). "To verify the relevance of these in vitro observations in COVID-19 patient samples, we measured twenty SARS-CoV-2 virus infected patient sera for detection of IL-6 and soluble IL-6R levels." (PMID 33284859, 2020). "Genentech started to recruit 330 severe COVID-19 patients from April in phase III clinical trial of Tocilizumab (NCT04320615), which is an inhibitor of IL-6." (PMID 33574756, 2020). "The inflammatory pathways are activated during COVID-19, and therefore parameters like C-reactive protein (CRP), ferritin, procalcitonin, fibrinogen, interleukin-6 (IL-6) were studied as prognostic factors." (PMID 32748880, 2020). "Indeed, a number of studies identified variants located in the regulatory regions of IL6 and IL6R as genetic determinants of high IL6 circulating levels in serum and tissues that have been proposed to affect the risk and progression of many different disease states (especially COVID-19, CVD and AD)." (PMID 33339153, 2020). "The anti-IL-6 monoclonal antibody tocilizumab is widely used to treat CRS in many other medical conditions and is now being used empirically in severe COVID-19 cases." (PMID 32685301, 2020). "Similar findings were reported in a cohort of over 1,5000 patients, where serum IL-6 and TNF-α were found to be independent predictors of disease severity and mortality in COVID-19 (Del Valleet al., 2020)." (PMID 33082935, 2020). "IL-6 as a major character both involved in “cytokine storm” after CPB and severe COVID-19 pneumonia may be a potential target therapy and prognostic value in COVID-19 patient who undergo cardiac surgery at greater risk to develop post-surgical adverse outcomes." (PMID 33505996, 2020). "Elevated serum concentrations of IL-6, tumor necrosis factor–α (TNF-α), and other inflammatory cytokines have been described in adults with COVID-19, particularly those who progress to ARDS." (PMID 32958614, 2020). "The elevated levels of cytokines IL-7, IL-10, IL-6, and IFN-α are indicative of severe inflammatory response and cytokine storm in COVID-19 patients." (PMID 32784499, 2020). "The prevalence of the pro- and anti-inflammatory cytokines interleukin receptor-2 (IL-2R), interleukin-6 (IL-6), tumor necrosis factor α (TNF-α) and IL-10 in severe and moderate cases of COVID-19 has also been studied." (PMID 32612515, 2020). "In particular, high levels of cytokine IL-6 pushed the clinical trials of specific inhibitors of this protein and of Janus kinase (JAK) on COVID-19 patients in China." (PMID 32847008, 2020). "Results showed that COVID-19 patients have higher serum level of cytokines (TNF-α, IFN-γ, IL-2, IL-4, IL-6 and IL-10) and CRP than control individuals." (PMID 32475230, 2020). "As exemplified above, IL-6 signalling is very important in ageing-related disorders, cancer, and severe viral diseases such as SARS, MERS and COVID-19." (PMID 33114676, 2020). "Elevated inflammatory markers, such as IL-6, hsCRP, LDH, ferritin, D-dimer, and procalcitonin, have been observed more frequently in severe cases of COVID-19 compared to non‐severe cases." (PMID 33335786, 2020).
COVID-19 (continued). "We also found that the inhibition of IL-6 signaling by tocilizumab treatment decreased PAI-1 production and alleviated clinical manifestations in severe COVID-19 patients." (PMID 32826331, 2020). "In conclusion, our findings suggest that both COVID-19 and AOSD have elevated level of ferritin and cytokines, including IL-1β, IL-6, IL-10, IL-18, and TNF-α, indicating systemic inflammation in the pathogenesis of COVID-19 and AOSD." (PMID 33552062, 2020). "In COVID-19 patients, disruption of the CCL5-CCR5 axis through CCR5 blocking antibody leronlimab was shown to reduce plasma IL-6, and SARS-CoV-2 plasma viremia." (PMID 32923679, 2020). "Similar to our findings in patients with bacterial CRS, the serum concentrations of IL-6, MCP-1, and IL-10 in all patients with severe COVID-19 were significantly elevated compared with those in healthy controls." (PMID 32826331, 2020). "We found that the CD4+ T cells in the peripheral blood were decreased in individuals infected with COVID-19 but that the levels of TNF-α and IL-6 in the plasma, which can be produced by CD4+ T cells, were significantly increased." (PMID 32976531, 2020). "High levels of interleukin IL-1β and IL-6 were detected in autopsy tissues from SARS-CoV patients and single cell RNA-seq analysis of peripheral blood in COVID-19 patients show increased subsets of CD14+ IL-1β-producing monocytes." (PMID 32655582, 2020). "Endotoxin stimulates the production of interleukin 6 (IL-6), IL-1, IL-8, tumor necrosis factor alpha (TNF-α), and gamma interferon (IFN-γ), cytokines that are also found in COVID-19 patients." (PMID 32703911, 2020). "Activation of NF-kB leading to ARDS in COVID-19 could be linked to the higher affinity of the S protein of SARS-CoV-2 with ACE2, leading to the release of angiotensin II via angiotensin receptor type 1, activating NF-kB and releasing proinflammatory cytokines such as IL-6." (PMID 32903279, 2020). "It exerts its effects likely through inhibiting the secretion of IL-1β, TNF-α, and IL-6 from macrophages/monocytes, which are a key cell population in ARDS development in COVID-19 patients." (PMID 32513951, 2020). "An elevation of serum levels of several cytokines such as interleukin (IL)-6, IL-10, and IFN-γ is reported in critically ill COVID-19 patients." (PMID 33203860, 2020). "Specifically, it correlates with lower levels of interleukin-6 (IL-6); a pro-inflammatory cytokine that regulates the cytokine storm, which leads to ARDS in COVID-19." (PMID 33396584, 2020). "The serum levels of IL-6 and CRP can effectively evaluate the severity and predict the prognosis in patients with COVID-19." (PMID 33062712, 2020). "A recent autopsy study of patients with COVID-19 shows that SARS-CoV-2 infection is detected in CD169+ macrophages that express the ACE2 molecule and produce IL-6." (PMID 32973814, 2020). "It is also possible that increased IL-6 leads to a reduction in CD4+ T cells and NK cells in patients with COVID-19 and immune dysregulation." (PMID 32849623, 2020). "In conclusion, several cytokine-blockers (anti-IL-6, anti-IL-1, anti-TNF-α etc.)are currently under investigation for COVID-19 patients that are already in use or currently tested for the treatment of irAE." (PMID 33207589, 2020). "However, there is evidence that the high viral load in the lungs of COVID-19 patients is associated with an acute inflammatory response comprising epithelial cells and activated macrophages, which are largely responsible for the secretion of the cytokines, such as TNF, IL-6, IL-8, IL-1β, and CXCL10." (PMID 33391014, 2020). "A combination of ICI with an anti-IL-6 antibody represents an attractive approach to reduce the risks for both irAEs and CRS frequently observed in severe COVID-19 cases." (PMID 33207589, 2020). "This systematic review concerns the efficacy of an interleukin-6 inhibitor, tocilizumab (TCZ) in reducing severe COVID-19 mortality." (PMID 33194450, 2020).
COVID-19 (continued). "This study suggests that severity of COVID-19 was characterized by increased TNF-α and IL-6 production." (PMID 32929061, 2020). "Activated T helper 1 (Th1) cells expressing IFN-γ, IL-6, and GM-CSF and inflammatory CD14+CD16+ monocytes secreting IL-6 and GM-CSF have been reported in COVID-19 patients with severe pneumonia." (PMID 32845937, 2020). "Multiple studies have shown that COVID-19 progression to ARDS is initiated by hypercytokinemia, but increased serum IL-6 concentration specifically was found to correlate with ICU admission, progression to ARDS and mortality." (PMID 32992775, 2020). "However, IL-6 has been shown to promote vasoconstriction in isolated pulmonary arteries; thus, it is conceivable that in addition to inflammation, it could mediate acute and chronic effects contributing to PH in COVID-19." (PMID 33138181, 2020). "Spike protein induced the generation of IL-6 in cultured cells as well as in COVID-19 positive patient sera, and AT1 receptor antagonist resulted in down-regulation of MAPK activation as well as IL-6 release." (PMID 33284859, 2020). "In a study of 46 patients with COVID-19-related ARDS, the levels of IL-6, IL-8, and TNF-α were lower compared with 51 SARS-CoV-2 negative patients with ARDS as a result of septic shock." (PMID 33505321, 2020). "Ibuprofen has been found to reduce IL-6 in human synovial fluid and in sputum; therefore, it will be important to report the use of ibuprofen (amongst other NSAIDs) in clinical studies of COVID-19 in order to better understand what impact it may have on cytokine production." (PMID 32797326, 2020). "TCM and its preparations can achieve an antipyretic effect by inhibiting 1L-1, IL-6, TNF-α, and other pyrogenic cytokines, and also can indirectly achieve the effect of initial treatment of COVID-19 by inhibiting the cytokine storm." (PMID 33013395, 2020). "We suggest that IL-6 and MCP-1 should be added to the list of candidate markers for disease prediction in COVID-19 patients with RF, as well as be further explored as targets for immune therapy with cytokine antagonists." (PMID 33303843, 2020). "In COVID-19, high levels of serum pro-inflammatory cytokines (IFN-γ, IL-1, IL-6, IL-12, and TGFβ) and chemokines (CCL2, CXCL10, CXCL9, and IL-8) have been reported to be detected in cases with severe disease compared to patients with uncomplicated SARS." (PMID 32733487, 2020). "During early disease, patients who proceeded to develop COVID-19 severe pneumonia (SP) and DHF had significantly higher levels of IL-6, IL-10 and MIP3α than those who developed mild illness." (PMID 33199778, 2020). "Our study shows a high in-hospital mortality rate in a cohort of elderly patients with COVID-19 and hypernatremia, lymphopenia, CVD other than hypertension, and higher IL-6 serum levels were identified as independent predictors of in-hospital mortality." (PMID 33257703, 2020). "Immunomodulation has emerged as a promising option for SOT recipients with COVID-19-related CRS, with available experience mainly restricted to the anti-IL-6 agent tocilizumab." (PMID 33110739, 2020). "A comparison performed with 40 patients showed an increase of IL-2, IL-6, IL-10, and IFN-γ in the serum of 13 patients with the severe form of COVID-19 compared to 27 cases of mild disease." (PMID 33584667, 2020). "Patients affected by obesity showed a severe consequence of COVID-19, due to the high concentrations of TNF-α, MCP-1 and IL-6 produced in the meantime by visceral and subcutaneous adipose tissue and by innate immunity." (PMID 33160363, 2020). "Elevated levels of pro-inflammatory cytokines, interleukin-1 (IL1β), interleukin-6 (IL6), and tumor necrosis factor-α (TNFα) in moderate to severe COVID-19 cases contribute to the hyperinflammatory response." (PMID 33490110, 2020).
COVID-19 (continued). "The expression of several cytokines identified in the current study (i.e., IL1B, IL-6, TNF, CCL2, CXCL9, and CXCL10) were also seen in bronchoalveolar lavage (BAL) cells from COVID-19 patients, providing further support to our observation." (PMID 32882823, 2020). "Several interventions have been shown to decrease IL-6 levels; in particular, behavioral interventions around physical activity, diet, and behavioral approaches to stress could be of benefit by potentially dampening the IL-6 production and other cytokine changes in COVID-19 progression." (PMID 33134238, 2020). "We used a multiplex cytokine assay to measure serum IL-6, IL-8, TNF, IL-1β, GM-CSF, IL-10, IL-33 and IFN-γ in 100 hospitalised patients with confirmed COVID-19 at admission to University Hospital Southampton (UK)." (PMID 32962703, 2020). "At the same time, T cell counts recovered was related to the concentration of cytokines in plasma likes IL-6, IL-10, and TNF-α, which was decreased in the disease resolution stage of COVID-19 patients." (PMID 33261583, 2020). "Under inflammatory conditions, such as COVID-19 and AOSD, ferritin is upregulated in response to IL-1β, IL-6, and IFN-γ." (PMID 33552062, 2020). "A retrospective cohort study including 41 COVID-19 patients observed that miR-9 levels were higher in individuals with COVID-19, particularly in non-survivors, and were strongly correlated with increased levels of IL-6, IL-1β, and TNF-α." (PMID 41595522, 2026). "CONCLUSIONS: MN-166 treatment was associated with faster recovery from respiratory failure in participants with COVID-19, independent of interleukin-6 antibody therapy." (PMID 41928198, 2026). "Independent of its antiviral effects, GQ20-PTO additionally suppressed IFNβ and IL-6 (but not TNFα) signaling and the formation of reactive oxygen species, processes known to contribute to hyperinflammation in severe COVID-19." (PMID 41851107, 2026). "Within a week of diagnosis, individuals who developed asymptomatic or mild COVID-19 could be distinguished by significantly increased mucosal IP-10 and decreased systemic IL-1RA, MIP-1β, IL-6, fractalkine, IgA, and IgM within one week of positive diagnostic." (PMID 41313205, 2026). "However, a change in therapeutic strategies during the first epidemic wave of COVID-19 due to the rapid acquisition of new knowledge, may have modified the IL-6 levels of the various cohorts, with a possible decrease after the widespread use of corticosteroids or anti-IL6." (PMID 40397955, 2025). "Cycle threshold (Ct) values of RT-qPCR testing were in negative correlation with IL-6 in COVID-19 male patients, indicating that higher viral load largely increased IL-6 levels in parallel with the severity of clinical outcome and regardless of vaccination." (PMID 40868247, 2025). "Notably, elevated IL-6 and lactate dehydrogenase (LDH) levels within 24 h of hospital admission have been identified as independent predictors of COVID-19 severity and poor outcomes." (PMID 41158128, 2025). "Two significant cytokines elevated during COVID-19, TNF-α and IL-6, directly affect brain physiology and may drive dysfunctional stress-related responses, mood alternations, and depressive symptoms." (PMID 40918512, 2025). "Ferritin, fibrinogen, and LDH were in positive correlation with IL-6 and clinical outcome of male COVID-19, while ferritin and LDH were in negative correlation with application and quantity of vaccines." (PMID 40868247, 2025). "In the post-COVID-19 group, INF-α2, MCP-1, and IL-6 differed significantly from controls." (PMID 40303405, 2025). "A recent study showed that IL-6 concentrations in COVID-19 immunosuppressed patients without autoimmune disease were significantly increased compared to COVID-19 patients without immunosuppression." (PMID 40489562, 2025). "Baseline values for IL-6 were lower than expected from studies in non-COVID-19 ARDS but were consistent with recent studies that have evaluated the inflammatory response in COVID-19." (PMID 40632387, 2025).